NSL1 (NSL1 component of MIS12 kinetochore complex)
Description:
Part of the MIS12 complex which is required for normal chromosome alignment and segregation and kinetochore formation during mitosis.
Synonyms: C1orf48; DC8; MIS14; DKFZP566O1646
Tractability: PROTAC: ubiquitination databases record sites on it; its protein half-life has been measured.
Gene: Protein-coding gene on chromosome 1 (212,726,153 to 212,791,783, reverse strand). Ensembl gene ENSG00000117697.
Subcellular location: Nucleus; Chromosome, centromere, kinetochore
Subcellular location (Human Protein Atlas): Nuclear speckles
Pathways (Reactome):
Cell Cycle: Amplification of signal from unattached kinetochores via a MAD2 inhibitory signal; EML4 and NUDC in mitotic spindle formation; Mitotic Prometaphase; Resolution of Sister Chromatid Cohesion; Separation of Sister Chromatids
Signal Transduction: RHO GTPases Activate Formins
Gene Ontology:
Molecular function: protein binding
Biological process: attachment of spindle microtubules to kinetochore; mitotic sister chromatid segregation
Cellular component: kinetochore; MIS12/MIND type complex; nuclear speck; nucleus; outer kinetochore; cytosol; spindle pole
Genetic constraint (gnomAD): Loss-of-function variants: 9 observed, 16 expected, observed/expected ratio (o/e) 0.56, 90% interval 0.34 to 0.98. The upper end of that interval is the gene's LOEUF score, 0.98, which puts it in group 4 of 6, group 1 being the genes least tolerant of losing a copy. Missense variants: 241 observed, 253.57 expected, observed/expected ratio (o/e) 0.95, 90% interval 0.86 to 1.06. Synonymous variants: 90 observed, 95.35 expected, observed/expected ratio (o/e) 0.94, 90% interval 0.8 to 1.12.
Homologues: Orthologues: chimpanzee NSL1 (99% identical), macaque NSL1 (98% identical), pig NSL1 (79% identical), mouse Nsl1 (67% identical), guinea pig NSL1 (64% identical), dog NSL1 (59% identical), rabbit NSL1 (54% identical), rat Nsl1 (41% identical), tropical clawed frog nsl1 (40% identical), zebrafish nsl1 (25% identical).
Diseases named in the same sentence as NSL1 in open-access papers:
NSL1 is named in the same sentence as 14 diseases in open-access papers, as found by Europe PMC text mining. Sharing a sentence is not in itself a finding about the gene and the disease. The quoted sentences say what the papers report.
Spastic paraplegia (1 paper, 2020). Complete loss of the ability to move the lower limbs accompanied by spasticity of the lower limbs. "In this family, which presented with ID, spastic paraplegia and visual impairments, two genetic variations within two different genes (NSL1 and RTL1) were identified." (PMID 31969655, 2020).
cancer (4 papers, 2020 to 2023). A tumor composed of atypical neoplastic, often pleomorphic cells that invade other tissues. "Based on the literatures included in PubMed, GPR12, ITM2B, ZNF24, and NSL1 were selected as the candidate targets due to the low expressions in various cancers." (PMID 37789353, 2023). "Best predicted cancer immunotherapy proteins with BC were RPS27, SUPT4H1, CLPSL2, POLR2K and RPL38, and the most altered ones were POLR2K, ASH2L, MED30, NSL1 and RPRD2." (PMID 32444848, 2020).
NSL1 also shares sentences with these, for which no sentence is quoted: malaria (23 papers); cerebral malaria (11); anemia (3); infection (3); tumor (3); cutaneous lupus erythematosus (1); glioma (1); melanoma (1); parasitemia (1); psoriasis (1); retinopathy (1); Thrombocytopenia (1).